GTF2H4 (general transcription factor IIH subunit 4)
Description:
Component of the general transcription and DNA repair factor IIH (TFIIH) core complex, which is involved in general and transcription-coupled nucleotide excision repair (NER) of damaged DNA and, when complexed to CAK, in RNA transcription by RNA polymerase II. In NER, TFIIH acts by opening DNA around the lesion to allow the excision of the damaged oligonucleotide and its replacement by a new DNA fragment. In transcription, TFIIH has an essential role in transcription initiation. When the pre-initiation complex (PIC) has been established, TFIIH is required for promoter opening and promoter escape. Phosphorylation of the C-terminal tail (CTD) of the largest subunit of RNA polymerase II by the kinase module CAK controls the initiation of transcription. Stimulates the ATPase activity of TFIIH subunit XPB/ERCC3.
Synonyms: TFB2; TFIIH; P52; XPJ
Tractability: Small molecule: a structure with a bound ligand is known. PROTAC: ubiquitination databases record sites on it; its protein half-life has been measured.
Gene: Protein-coding gene on chromosome 6 (30,907,522 to 30,914,119, forward strand). Ensembl gene ENSG00000213780.
Subcellular location: Nucleus
Subcellular location (Human Protein Atlas): Nuclear speckles
Pathways (Reactome):
Gene expression (Transcription): Formation of RNA Pol II elongation complex; Formation of the Early Elongation Complex; NoRC negatively regulates rRNA expression; RNA Pol II CTD phosphorylation and interaction with CE; RNA Polymerase I Promoter Escape; RNA Polymerase I Transcription Initiation; RNA Polymerase I Transcription Termination; RNA Polymerase II Pre-transcription Events; RNA Polymerase II Promoter Escape; RNA Polymerase II Transcription Elongation; RNA Polymerase II Transcription Initiation; RNA Polymerase II Transcription Initiation And Promoter Clearance; RNA Polymerase II Transcription Pre-Initiation And Promoter Opening
Disease: Formation of HIV elongation complex in the absence of HIV Tat; Formation of HIV-1 elongation complex containing HIV-1 Tat; Formation of the HIV-1 Early Elongation Complex; HIV Transcription Initiation; RNA Pol II CTD phosphorylation and interaction with CE during HIV infection; RNA Polymerase II HIV Promoter Escape; Tat-mediated elongation of the HIV-1 transcript; Transcription of the HIV genome
DNA Repair: Dual Incision in GG-NER; Dual incision in TC-NER; Formation of Incision Complex in GG-NER; Formation of TC-NER Pre-Incision Complex; Gap-filling DNA repair synthesis and ligation in TC-NER; Transcription-Coupled Nucleotide Excision Repair (TC-NER)
Metabolism of RNA: mRNA Capping
Gene Ontology:
Molecular function: protein binding; RNA polymerase II general transcription initiation factor activity; double-stranded DNA binding; ATPase activator activity
Biological process: transcription by RNA polymerase II; DNA repair; nucleotide-excision repair; transcription initiation at RNA polymerase II promoter
Cellular component: core TFIIH complex portion of holo TFIIH complex; nuclear speck; nucleus; transcription factor TFIID complex; transcription factor TFIIH holo complex; nucleoplasm; transcription factor TFIIH core complex
Genetic constraint (gnomAD): Loss-of-function variants: 48 observed, 62.06 expected, observed/expected ratio (o/e) 0.77, 90% interval 0.61 to 0.98. The synonymous counts are far from expectation, so gnomAD's model fits this gene poorly and the ratio says little. Missense variants: 475 observed, 599.77 expected, observed/expected ratio (o/e) 0.79, 90% interval 0.73 to 0.85. Synonymous variants: 188 observed, 241.03 expected, observed/expected ratio (o/e) 0.78, 90% interval 0.69 to 0.88.
Homologues: Orthologues: chimpanzee GTF2H4 (100% identical), macaque GTF2H4 (100% identical), pig GTF2H4 (99% identical), dog GTF2H4 (99% identical), guinea pig GTF2H4 (99% identical), rat Gtf2h4 (99% identical), mouse Gtf2h4 (99% identical), rabbit GTF2H4 (99% identical), tropical clawed frog gtf2h4 (83% identical), zebrafish gtf2h4 (77% identical), Drosophila melanogaster mrn (52% identical), Caenorhabditis elegans gtf-2H4 (33% identical).
Diseases named in the same sentence as GTF2H4 in open-access papers:
GTF2H4 is named in the same sentence as 20 diseases in open-access papers, as found by Europe PMC text mining. Sharing a sentence is not in itself a finding about the gene and the disease. The quoted sentences say what the papers report.
cervical carcinoma (4 papers, 2010 to 2021). A carcinoma arising from either the exocervical squamous epithelium or the endocervical glandular epithelium. "However, GTF2H4 is located on chromosome 6p21.3 within the HLA region and is thus of note as a number of studies have investigated HLA Class II and I genes with cervical cancer and have consistently identified alleles (e.g., HLA-DRB*1301) associated with cervical cancer." (PMID 20084279, 2010).
age-related macular degeneration (2 papers, 2019 to 2022). Age-related loss of vision in the central portion of the retina (macula), secondary to retinal degeneration. "One study reported the association of a CpG site at CDKN2B in normal-tension glaucoma, another study found CpG sites at SKI and GTF2H4 in the retinal pigment epithelium of age-related macular degeneration patients." (PMID 35741817, 2022).
breast carcinoma (2 papers, 2020 to 2024). "GTF2H4 has been identified to be related to the survival risk of breast cancer." (PMID 32461838, 2020).
xeroderma pigmentosum (2 papers, 2025). Xeroderma pigmentosum (XP) is a rare genodermatosis characterized by extreme sensitivity to ultraviolet (UV)-induced changes in the skin and eyes, and multiple skin cancers. "This approach was inspired by the diagnosis and molecular dissection of a xeroderma pigmentosum (XP) case with mutations in GTF2H4, encoding the TFIIH-p52 subunit." (PMID 40924495, 2025).
autoimmune disease (1 paper, 2025). A disorder resulting from loss of function or tissue destruction of an organ or multiple organs, arising from humoral or cellular immune responses of the individual to their own tissue constituents. "Our Bayesian colocalization analysis revealed five genes, including GTF2H4, FLOT1, HCP5, immediate early response 3 (IER3), and serine/threonine kinase 19 (STK19), that were identified as having a shared variant with autoimmune diseases (PP.H4 > 0.8)." (PMID 40599891, 2025).
multiple sclerosis (1 paper, 2012). A progressive autoimmune disorder affecting the central nervous system resulting in demyelination. "Recruitment and activation of Gtf2h4 represents a rate-limiting step for the emergence of HIV from latency and sequence variants have been associated with multiple sclerosis." (PMID 22905720, 2012).
viral infection (1 paper, 2010). "In this population-based study, we found nine genes/regions associated with CIN3/cancer, 6 of which remained significant at a FDR≤0.2 – three DNA repair genes (GTF2H4, DUT, and DMC1) and three viral infection and cell entry related genes (OAS3, SULF1, and IFNG)." (PMID 20084279, 2010).
cancer (2 papers, 2010 to 2022). A tumor composed of atypical neoplastic, often pleomorphic cells that invade other tissues. "For example, FAM115C is related to cancer cell migration, and GTF2H4 plays a key role in DNA repair and has been reported to be associated with the risk for human papillomavirus (HPV) resistance in Costa Ricans." (PMID 35864541, 2022). "From each region, the single most significant SNPs associated with CIN3/cancer were OAS3 rs12302655, SULF1 rs4737999, IFNG rs11177074, DUT rs3784621, DMC1 rs5757133, GTF2H4 rs2894054, EVER1/EVER2 rs9893818 (p-trends≤0.001)." (PMID 20084279, 2010). "SNPs for OAS3, SULF1, DUT, and GTF2H4 were associated with HPV persistence whereas IFNG and EVER1/EVER2 SNPs were associated with progression to CIN3/cancer." (PMID 20084279, 2010).
tumor (2 papers, 2023 to 2025). "To reveal potential transcription factors involved in CSC maintenance, we extracted the top 20 transcription factors differentially expressed in stem‐like tumor spheres and identified two transcriptional factors, YY2 and GTF2H4, as having the most altered expression." (PMID 37300334, 2023).
GTF2H4 also shares sentences with these, for which no sentence is quoted: lung carcinoma (2 papers); cervical intraepithelial neoplasia (1); epidermodysplasia verruciformis (1); ischemic disease (1); lung squamous cell carcinoma (1); lymph node metastasis (1); normal-tension glaucoma (1); ovarian carcinoma (1); prostate carcinoma (1); renal cell cancer (1); Sepsis (1).